WEE1 (WEE1 G2 checkpoint kinase)
Diseases named in the same sentence as WEE1 in open-access papers (continued):
Sharing a sentence is not in itself a finding about the gene and the disease.
leukemia (37 papers, 2011 to 2025). A malignant (clonal) hematologic disorder, involving hematopoietic stem cells and characterized by the presence of primitive or atypical myeloid or lymphoid cells in the bone marrow and the blood. "Upregulation of Wee1 is not only associated with cancerogenesis including hepatocellular carcinoma, breast cancer, lung cancer, and leukemia but also related to tumor progression, poor disease-free survival, and worse prognosis." (PMID 36575478, 2022). "To determine whether SRSF2 mutations alone are sufficient to sensitize leukemia cells to ATR/CHK1/WEE1 inhibition, we modeled the mutations in two complementary systems: (i) isogenic human K562 cell lines and (ii) knock-in mouse bone marrow progenitors." (PMID 41279606, 2025). "Moreover, several other clinical trials have shown that WEE1 inhibitors, in combination with other agents, are effective against pancreatic cancer, non-small-cell lung cancer, and leukemia with KRAS mutations." (PMID 39335109, 2024). "Furthermore, besides the well-known leukemia-related genes, our analysis also identified novel potential driver mutations, such as WEE1, associated with selective expression of mutated alleles in HeH ALL." (PMID 39369032, 2024). "We first investigated Wee1 expression on CML cells and discovered that Wee1 was upregulated in leukemia cell lines compared to TK6 in terms of both mRNA and protein expression." (PMID 36575478, 2022). "For example, 17p loss increases resistance to seven different drugs in leukaemia (LAML) and five of these target cell cycle/mitotic regulators (KIF11, CDK2/7/9, WEE1, PLK1, microtubules)." (PMID 31974379, 2020). "WEE1 was expressed at high levels in various cancer types including leukemia and was a validated target of the miR-17-92 cluster in leukemia, giving support to our prediction of miR-17-WEE1 axis in AML." (PMID 31164492, 2019). "Treatment of solid cancers and leukaemia with inhibitors of the cell cycle regulator WEE1 has proven successful in early clinical trials, as WEE1 inhibitors result in cell cycle disruption, induction of DNA damage and eventually, induction of apoptosis." (PMID 31703356, 2019). "Among different leukemia subtypes, Wee1 was significantly higher in BCR-ABL1-negative samples (diagnosis p = 0.0061; relapse p = 0.005) than in BCR-ABL1-positive samples (diagnosis ns; relapse p = 0.01) compared with normal MNCs." (PMID 30068368, 2018). "We first demonstrated that AZD1775 effectively inhibits WEE1 kinase activity in vivo at the dose administered by performing flow cytometry for phospho-CDK in human leukemia cells harvested from mice." (PMID 26334102, 2015). "Inhibition of WEE1 with AZD1775 sensitizes T-ALL to several anti-leukemia agents, particularly cytarabine." (PMID 26334102, 2015). "Lastly, we demonstrated that AZD1775 inhibits WEE1 function in leukemia cells in vivo, delays leukemia progression and prolongs survival better than cytarabine alone." (PMID 26334102, 2015). "Overexpression of Wee1 kinase has been reported in other tumor types, including brain tumors and leukemia, and the usefulness of Wee1 kinase inhibitor has been demonstrated." (PMID 24960176, 2014). "To determine whether SRSF2 mutations are sufficient to sensitize leukemia cells to inhibition of ATR, CHK1, and WEE1, we tested the sensitivity of ten isogenic SRSF2 mutant and four wild-type K562 clones to inhibitors of these kinases." (PMID 41279606, 2025). "Combination therapies with WEE1 inhibitors may be attractive in this setting, reducing leukemia burden by inducing cell death through the cell-intrinsic mechanism, as characterized here." (PMID 38822412, 2024).
leukemia (continued). "Given prior reports of synergy between CHEK1 and WEE1 inhibitors in lymphoma, leukemia, and solid tumor cell lines, we suspected that simultaneous inhibition of CHEK1 and WEE1 might further magnify the synthetic lethal effect with RAD17 knockdown." (PMID 26437225, 2015). "Our data builds on mounting evidence that WEE1 inhibition may augment the effect of chemotherapy for the treatment of leukemias." (PMID 26334102, 2015). "Thus, acquired resistance to WEE1 inhibition may be reversed by HDAC or BRD4 inhibition in leukemia cells." (PMID 32195191, 2020). "Combining treatment with DOCK2 knockdown and DDR inhibitors such as CHK1 inhibitor MK876, WEE1 inhibitor MK1775, and RAD51 inhibitor 1302 significantly enhanced the sensitivity of mice with FLT3-ITD mutant leukemia cells to cytarabine." (PMID 36250020, 2022). "Our results show that several low toxicity drugs, already in clinical use for ALL or other non-communicable disease, potentiate the efficacy of WEE1 inhibitors in leukemia to overcome this challenge." (PMID 38822412, 2024). "Indeed, blocking of WEE1 activity with AZD1775 results in apoptosis in solid cancers, lymphoma, and leukaemia." (PMID 31703356, 2019). "Consistent with our previous results using inhibitors that target Chk1 and Chk2 checkpoint kinases, the sensitivity to AZD-1775 did not correlate with leukemia subtypes, karyotype, or with the basal expression of WEE1 (data not shown)." (PMID 30068368, 2018). "Interestingly, the leukemia cells were able to recover after treatment with AZD1775 and doxorubicin, suggesting that WEE1 inhibition may be most toxic with anti-metabolite chemotherapeutics." (PMID 26334102, 2015). "To determine whether inhibition of WEE1 sensitizes ALL cell lines to clinically relevant chemotherapeutics, we first treated Jurkat cells with a panel of clinically relevant anti-leukemia agents with a range of doses to estimate the dose that inhibited proliferation by 50% (IC50)." (PMID 26334102, 2015).
gastric cancer (31 papers, 2012 to 2025). A primary or metastatic malignant neoplasm involving the stomach. "Thus, the WEE1 inhibitor MK1775 specifically enhanced the anticancer effect of immune checkpoint blockade therapy in MUS81 deficient gastric cancer cells." (PMID 34625086, 2021). "Furthermore, male gastric cancer patients with advanced lymph node metastases had high expression of WEE1 and were associated with poor survival probability." (PMID 27363019, 2016). "Also, massive lymph node metastasis of male gastric cancer patients was associated with high expression of WEE1." (PMID 27363019, 2016). "Gastric cancer cells exhibiting high expression of WEE1 displayed increased susceptibility to WEE1 inhibitory therapy, indicating that the efficacy of WEE1 inhibition may be dependent on the expression level of WEE1 kinase." (PMID 38231277, 2024). "However, the anti-gastric cancer potentials as well as the underlying mechanisms of targeting Wee1 with DNA-damaging agents, particularly cisplatin, remain largely unknown." (PMID 29977914, 2018). "WEE1 has an elevated expression in a number of cancer types, including adult GBMs, and breast, colon, and stomach cancers." (PMID 37114037, 2023). "Other studies have shown similar results in gastric cancer cell lines after Wee1 siRNA-mediated knockdown or adavosertib treatment, although the mechanism of action was not elucidated." (PMID 36081565, 2022). "Eventually, WEE1 inhibition triggers gastric cancer cell-intrinsic innate immunity through the activation of the cGAS/STING pathway, and thus, potentiates the anticancer effect of ICB therapy in MUS81 deficient gastric cancer cells." (PMID 34625086, 2021). "The expression of WEE1 showed limited change at the transcription level, but consistent with our observations in gastric cancer tissues, the WEE1 protein level was significantly elevated in MUS81 knockdown cells." (PMID 34625086, 2021). "Consistent with our results, a previous report showed that knockdown of Wee1 by siRNA decreases the migration and invasion of gastric cancer cells." (PMID 31427973, 2019). "We show that high-expression of WEE1 at stage 4 showed a statistically significant poor survival rate compared to the expression level of early stage gastric cancer patients." (PMID 27363019, 2016). "To determine the function of WEE1 in gastric cancer cells, we determined that WEE1 ablation decreased the proliferation, migration, and invasion, while overexpression of WEE1 increased these effects in gastric cancer cells." (PMID 27363019, 2016). "In this study, we investigated the oncogenic role and therapeutic potency of targeting WEE1 in gastric cancer." (PMID 27363019, 2016). "Inhibition of WEE1 led to decreased cell viability, invasion, and migration of WEE1 high-expressed gastric cancer cells, whereas WEE1 overexpression reversed these effects in WEE1 low-expressed gastric cancer cells." (PMID 27363019, 2016). "At first, higher expression levels of WEE1 with lower survival probability were determined in stage 4 gastric cancer patients or male patients with accompanied lymph node metastasis." (PMID 27363019, 2016). "The Wee1 inhibitor AZD1775 has an effective checkpoint inhibitory activation effect, which can significantly inhibit the proliferation of gastric cancer cells and induce apoptosis and cell cycle arrest, especially in gastric cancer cells with high Wee1 expression." (PMID 36035159, 2022). "Our study reports that MUS81 targeting could enhance the immune-modulating effect of WEE1 inhibitors, and this might promote new strategies and overcome obstacles during clinical treatment of patients with advanced gastric cancer." (PMID 34625086, 2021). "Our observations led us to next evaluate whether targeting MUS81 could elevate the anticancer effect of WEE1 inhibitors in gastric cancer cells." (PMID 34625086, 2021).
gastric cancer (continued). "Indeed, overexpression of Wee1 significantly promotes the proliferation, migration, and invasion in gastric cancer cells; Vice versa, RNA interference (RNAi)-mediated knockdown of Wee1 dramatically suppresses these effects." (PMID 31427973, 2019). "Based on the mechanisms by which Wee1 inhibitor and cisplatin played their own role, a promising strategy of Wee1 inhibitor combined with cisplatin was proposed, which was investigated in gastric cancer (GC)." (PMID 29977914, 2018). "However, male gastric cancer patients showed high-expression of WEE1 with poor survival probability." (PMID 27363019, 2016). "Ablation of WEE1 significantly reduced invasion and migration in gastric cancer cells." (PMID 27363019, 2016). "We also suggest that AZD1775, a WEE1 inhibitor, could be a potent anti-gastric cancer agent that could be applied in clinical trials." (PMID 27363019, 2016). "Therefore, we started this study to identify the role of WEE1 in proliferation and motility in gastric cancer, and we also determined the potential for making WEE1 a therapeutic target in gastric cancer." (PMID 27363019, 2016). "Over-expression of WEE1 increased gastric cancer cell invasion and migration." (PMID 27363019, 2016). "However, male gastric cancer patients with lymph node metastasis stage 1-3 showed a correlation with poor prognosis and higher WEE1 expression." (PMID 27363019, 2016). "This suggests that WEE1 regulates the cell proliferation and motility of gastric cancer cells." (PMID 27363019, 2016). "Taken together, we propose that WEE1 is over-expressed and could enhance gastric cancer cell proliferation and metastasis." (PMID 27363019, 2016). "Therefore, in gastric cancer, WEE1 inhibitors are used to enhance the efficacy of immunotherapy." (PMID 39759116, 2025). "Therefore, we further investigated in vitro and in vivo whether targeting WEE1 has therapeutic potential in gastric cancer." (PMID 27363019, 2016). "Therefore, we suggest that WEE1 is a potent target for gastric cancer therapy." (PMID 27363019, 2016). "Taken together, we demonstrate that high expression of WEE1 in advanced stages and/or accompanied with lymph node metastasis indicate poorer survival for gastric cancer patients and that targeting WEE1 would be a therapeutic benefit for gastric cancer patients." (PMID 27363019, 2016). "In gastric cancer, MUS81-EME1 disrupts β-TRCP-induced ubiquitination and increases the expression of WEE1, which acts as a DNA-damage checkpoint kinase and inhibits the activation of the intrinsic immune cGAS-STING pathway." (PMID 39759116, 2025). "Ropivacaine inhibits gastric cancer invasion, migration, and growth by downregulating PI3K/AKT and WEE1 via miR-520a-3p." (PMID 40713692, 2025). "Our study found that high MUS81 expression indicates poor prognosis in gastric cancer and that targeting MUS81 elevates the expression of WEE1 owing to the disruption of β-TRCP-induced ubiquitination." (PMID 34625086, 2021). "Ropivacaine represses the invasion, migration, and growth of gastric cancer by attenuating PI3K/AKT and WEE1 signaling through miR-520a-3p." (PMID 34126594, 2021). "In summary, we provided reliable data to demonstrate that MUS81 targeting amplified the activation of innate immune response and promoted the anticancer effect of WEE1 inhibitor and ICB combination therapy in gastric cancer." (PMID 34625086, 2021). "In this study, we showed the effect of the WEE1 inhibitor, AZD1775, on gastric cancer cells." (PMID 27363019, 2016). "It has been known that WEE1 is highly expressed and has oncogenic functions in various cancers, but it is not yet studied in gastric cancers." (PMID 27363019, 2016). "Overall survival rates for the gastric cancer patients were not significant based on expression of WEE1 (data not shown)." (PMID 27363019, 2016).
gastric cancer (continued). "Although the WEE1 inhibitor MK1775 partly enhanced the anticancer effect of PD-L1 inhibitors by activating the cGAS/STING pathway, MUS81 targeting further amplified the anticancer effect of this combination strategy because of the elevated cytosolic dsDNA in gastric cancer cells." (PMID 34625086, 2021). "However, the study of WEE1 in gastric cancer cells has not been reported yet." (PMID 27363019, 2016). "Furthermore, we performed IHC staining of specimens from a cohort of 26 patients with gastric cancer and observed a significant negative correlation between MUS81 and WEE1 kinase expression (Pearson r = −0.52, P = 0.0063)." (PMID 34625086, 2021).
acute myeloid leukemia (28 papers, 2013 to 2025). Acute myeloid leukemia (AML) is a group of neoplasms arising from precursor cells committed to the myeloid cell-line differentiation. "Similar results on the role of WEE1 were obtained in multiple myeloma (MM), acute myeloid leukemia (AML), chronic myeloid leukemia (CML), and chronic lymphocyte leukemia (CLL)." (PMID 32958072, 2020). "Similarly a functional genomic approach in acute myeloid leukemia also identified WEE1 as a key regulator of chemotherapy sensitivity." (PMID 24661910, 2014). "We, and others, identified WEE1 as a critical mediator of acute myeloid leukemia (AML) cell survival after exposure to cytarabine." (PMID 26334102, 2015). "In acute myeloid leukemia, combination treatment of CUDC-907 with Wee1 inhibitor adavosertib showed a synergistic effect in both AML cell lines and primary specimens by enhancing the adavosertib-initiated DNA damage." (PMID 41148814, 2025). "In combination with WEE1 inhibition, impaired activity of the cell cycle checkpoint kinase and premature mitotic entry lead to an increase in DNA damage and apoptosis, making this combination a promising target for the treatment of acute myeloid leukemia (AML)." (PMID 41375077, 2025). "Similarly, a notable observation was made regarding the combined effect of mTOR inhibitor and WEE1 inhibitor in both mutant neuroblastoma NRAS- and mutant KRAS-positive acute myelogenous leukemia (AML) cell lines and primary patient samples." (PMID 38231277, 2024). "Wee1 is found to be overexpressed in hematological tumors such as acute lymphoblastic leukemia (ALL), acute myeloid leukemia (AML), chronic myeloid leukemia (CML), chronic lymphocyte leukemia (CLL), multiple myeloma (MM), and diffuse large B cell lymphoma (DLBCL)." (PMID 33498235, 2021).
non-small cell lung carcinoma (27 papers, 2011 to 2025). A group of at least three distinct histological types of lung cancer, including non-small cell squamous cell carcinoma, adenocarcinoma, and large cell carcinoma. "In non-small-cell lung cancer, on the other hand, reduced Wee1 expression was associated with a higher recurrence rate." (PMID 22719872, 2012). "Another study of 663 advanced non-small cell lung cancer patients showed that WEE1 rs3910384 genotype was markedly correlated with prognosis following platinum-based chemotherapy as well as the combined efficacy of platinum and gemcitabine." (PMID 38231277, 2024). "Moreover, quercetin treatment increases the radiosensitivity of non-small cell lung cancer (NSCLC) cells by downregulating miR-16-5p and interfering with the miR-16-5p/WEE1 axis." (PMID 35971151, 2022). "Accordingly, the WEE1 inhibitor AZD1775 sensitizes gastric, non-small cell lung cancer (NSCLC), and pancreatic cancer to olaparib, particularly when combined with genotoxic stress via ionizing radiation, and a small number of clinical trials are currently underway." (PMID 35681619, 2022). "The treatment of non-small cell lung cancer cells (A549 and NCI-H1975) with Nag-E was found to induce G2/M phase cell cycle arrest through down-regulation of the protein kinase Wee1, the protein Cyclin B1 and reduction of the phosphorylation of cyclin-dependent kinases cdc2 and cdc25C." (PMID 33034879, 2020).
viral infection (26 papers, 2012 to 2025). "Deletion of miR-155-5p reduces the capability of CD8+ cytotoxic T cells to respond to viral infection or tumor development, and aberrant expression of miR155-5p correlates with inflammation through targeting and degrading SHIP1 and WEE1 genes involved in inflammation." (PMID 35086548, 2022).